DES (desmin)
Diseases named in the same sentence as DES in open-access papers (continued):
Sharing a sentence is not in itself a finding about the gene and the disease.
Arrhythmia (9 papers, 2015 to 2025). Any cardiac rhythm other than the normal sinus rhythm. "They formed a ternary assembled with desmin and desmoplakin and showed that deficient iASPP in mice led to ventricular tachycardia, arrhythmia, ACM, and sudden death." (PMID 35933355, 2022). "This is supported by previous studies, which showed that genetic variations of DES and loss of desmin expression trigger cardiac arrhythmia." (PMID 36158202, 2022). "These alterations are known to play a role in cardiac arrhythmias, therefore a possible association between desmin disruption and the onset of cardiac arrhythmias has been suggested." (PMID 36158202, 2022). "On the molecular level, impaired desmin causes severe filament assembly defects, desmin aggregation, and abnormal distribution of Ca2+, that collectively may drive cardiac arrhythmias and cardiac conduction defects." (PMID 36158202, 2022). "Other genes include lamin A/C (LMNA), linked to a high risk of arrhythmias and sudden cardiac death, filamin C (FLNC), phospholamban (PLN), β-myosin heavy chain (MYH7), cardiac troponin T (TNT2) and desmin (DES)." (PMID 41464586, 2025). "Although there are no clear and effective treatment methods and drugs for impaired desmin-induced cardiac arrhythmia, some complications can be prevented." (PMID 36158202, 2022). "As desmin is highly expressed in structures of the cardiac conduction system, the majority of pathogenic DES variants cause cardiac arrhythmia and cardiac conduction defects." (PMID 36158202, 2022). "This review will provide up-to-date insight into the molecular and cellular mechanisms of desmin to underlie a healthy cardiac conduction system and how impaired desmin triggers cardiac arrhythmias, including AF." (PMID 36158202, 2022). "Here, the molecular and cellular mechanisms of desmin to underlie a healthy cardiac conduction system and how impaired desmin triggers cardiac arrhythmias, including atrial fibrillation, are discussed." (PMID 36158202, 2022). "Finally, potential implications for future clinical treatments of cardiac arrhythmias directed at desmin are discussed." (PMID 36158202, 2022). "Finally, potential implications for future clinical treatments of cardiac arrhythmias directed at desmin are highlighted." (PMID 36158202, 2022). "Furthermore, an overview of available (genetic) desmin model systems for experimental cardiac arrhythmia studies is provided." (PMID 36158202, 2022). "Furthermore, an overview of available genetic desmin model systems for experimental cardiac arrhythmia is provided." (PMID 36158202, 2022).
fibrosarcoma (9 papers, 2013 to 2026). A malignant mesenchymal fibroblastic neoplasm affecting the soft tissue and bone. "This distinguishes these lesions from fibrosarcoma, which should stain for both desmin and caldesmon." (PMID 23607022, 2013). "Histopathology showed low-grade fibrosarcoma; immunohistochemistry was positive for Vimentin and SMA, focally CD34, and negative for S100, Desmin, and Myogenin, with low Ki-67 (<3 %)." (PMID 41045685, 2025). "Consistent with the immunophenotypic profile of low-grade malignant fibrosarcoma, only Vimentin is expressed in immunohistochemistry; SMA may show positive expression in instances of myofibroblastic differentiation; Desmin, CK, EMA, and CD34 were non-reactive." (PMID 39968290, 2024). "These infantile fibrosarcomas were diffusely and robustly positive for Trk (100%), S100 protein (50%, 3/6 cases), nestin, CD10 (80%, 4/5 cases), and vimentin (100%), but negative for CD34, SMA, desmin, myogenin, and CD56." (PMID 32957984, 2020).
myopericytoma (9 papers, 2013 to 2025). A usually slow growing, subcutaneous nodular neoplasm arising from myopericytes. "Whereas up to 25% of myopericytomas are desmin-positive, desmin positivity has rarely been reported in myofibromas." (PMID 23742153, 2013). "In addition, the tumor cells of myopericytoma have been found to express immunopositivity for desmin in a few cases." (PMID 24348865, 2014). "In IHC of myopericytoma, α-SMA and h-caldesmon are positive, while desmin and CD34 show focal positivity." (PMID 40599523, 2025). "Right hemihepatectomy was performed and histopathological examination revealed a well-circumscribed mass consistent with myopericytoma, supported by positive immunohistochemical staining for SMA and H caldesmon, and negativity for Desmin, DOG-1, and ALK." (PMID 40043410, 2025). "Angiomyolipoma is similar to myopericytoma in morphological features, and expresses immunoreactivity for HMB-45, S-100 and desmin, whereas myopericytoma rarely expresses immunoreactivity for desmin." (PMID 24348865, 2014). "By immunohistochemistry, myopericytomas usually show a desmin-negative, actin-positive phenotype." (PMID 40522461, 2025).
rhabdomyoma (9 papers, 2012 to 2026). A benign mesenchymal tumor arising from skeletal or cardiac muscle. "Repeated vobra duo doses ameliorated this outcome, reverting rhabdomyosarcorma to rhabdomyoma tumor, by increasing Desmin and Myogenin/Myf-4 differentiation markers expression, and reducing both Ki-67 and CD133." (PMID 41507126, 2026). "Adult rhabdomyoma staining will characteristically confirm skeletal muscle differentiation, with tumours positive for myoglobin, desmin and muscle-specific actin." (PMID 29744825, 2019). "Immunohistochemical studies show the striated muscle characteristics of rhabdomyoma cells, which express myoglobin, desmin, and actin." (PMID 22973317, 2012). "Immunohistochemical staining was positive for MSA, Desmin, MYOD1 and Myogenin, leading to a final pathological diagnosis of adult rhabdomyoma." (PMID 39963349, 2025). "The immunohistochemical features of rhabdomyoma are identical to those of normal skeletal muscle cells because it shows cytoplasmic positivity for MSA (muscle-specific actin), desmin." (PMID 23259131, 2012).
sarcomatoid carcinoma (9 papers, 2010 to 2025). A malignant epithelial neoplasm characterized by the presence of spindle cells and anaplastic morphologic features. "The spindle cells of sarcomatoid carcinomas often label for actin, although desmin is not frequently expressed." (PMID 21143956, 2010). "As other immunohistochemical markers were negative, including CD45, CD163, CD68, Desmin, Myogenin, Melanoma, S100, α-SMA, Cytokeratin 7, Cytokeratin 20, MDM2 and CDK4, the tumors were diagnosed as sarcomatoid carcinomas." (PMID 29874846, 2018). "Desmin and myogenin immunoreactivity can be used to differentiate RMS from other round cell tumors without rhabdomyoblastic differentiation but not sarcomatoid carcinoma with rhabdomyoblastic differentiation." (PMID 30390704, 2018).
soft tissue sarcoma (9 papers, 2007 to 2025). A malignant neoplasm arising from muscle tissue, adipose tissue, blood vessels, fibrous tissue, or other supportive tissues excluding the bones. "Staining with desmin and MyoD, markers used clinically in evaluating soft tissue sarcomas, validated the skeletal muscle phenotype required for the assignment of RMS (bottom)." (PMID 26496700, 2015).
spindle cell sarcoma (9 papers, 2006 to 2025). A malignant mesenchymal neoplasm composed of spindle-shaped cells. "Resection specimen of the same case showed spindle cell sarcoma in a herring bone pattern, which on immunohistochemistry was negative for all specific lineage markers like smooth muscle actin, desmin, myogenin, pancytokeratin etc." (PMID 29204102, 2017). "Histological examination revealed a spindle cell sarcoma corresponding to a dedifferentiated liposarcoma with leiomyosarcomatous features as murine double minute 2 translocation was identified by fluorescence in situ hybridization and desmin by immunohistochemistry." (PMID 39252749, 2024). "Postoperative pathological results confirmed the renal vein leiomyosarcoma: spindle cell sarcoma, diffuse severe atypia, S-100 (-), SMA ( +), desmin ( +), CD34 (−), CD99 ( +)." (PMID 35761392, 2022). "Pathology revealed spindle cell sarcoma, diffuse severe atypia, S-100 (−), SMA (+), desmin (+), CD34 (−), CD99 (+)." (PMID 35761392, 2022). "After extensive immunohistochemical analysis, including antibodies against pan-cytokeratin, S100, CD34, beta-catenin, SMA, desmin, CD10 and MDM2, the tumor was classified as high-grade spindle cell sarcoma NOS." (PMID 35645621, 2022). "Immunohistochemical staining showed positive immunoreactivity for vimentin and negative for desmin, SMA and CD34 antibodies that are useful to distinguish this type of cancer from other spindle cell sarcomas." (PMID 40788189, 2025).
alveolar rhabdomyosarcoma (8 papers, 2005 to 2025). A rapidly growing malignant mesenchymal neoplasm. "For instance, the diagnosis of alveolar rhabdomyosarcoma (ARMS) is typically based on histopathological features, IHC results (most importantly desmin, MyoD1, and myogenin), and molecular results (RT-PCR for PAX3/PAX7–FOXO1 or FISH for PAX3/FOXO1 rearrangement)." (PMID 37621777, 2023).
angiomyolipoma (8 papers, 2012 to 2025). A neoplasm with perivascular epithelioid cell differentiation often associated with tuberous sclerosis. "The presence of perivascular epithelioid cells (PEC) is often used to characterize angiomyolipomas since these cells show immunoreactivity for muscle markers (epithelial membrane antigen, keratin, vimentin, desmin, and actin) and HMB-45." (PMID 24555133, 2012).
angiosarcoma (8 papers, 2011 to 2024). A malignant tumor arising from the endothelial cells of the blood vessels. "From its hyalinizing pseudovascular appearance and sometimes focal and dot-like desmin and myogenin expression, these tumors could easily be mistaken for variants of angiosarcoma, extraskeletal myxoid chondrosarcoma, osteosarcoma, or sclerosing epithelioid fibrosarcoma." (PMID 23766666, 2013). "Immunohistochemical profiling is essential for differentiating PASH from low-grade angiosarcoma, with specific markers such as CD34, vimentin, desmin, actin, and progesterone receptor aiding in the correct diagnosis and preventing misinterpretation." (PMID 39564024, 2024). "In our case a diagnosis of high grade angiosarcoma was confirmed by strong and diffuse positive reaction for CD31, along with negative cytokeratin and desmin stains." (PMID 22185665, 2011). "The tumor cells were negative for desmin, HHF35, HMB45, Melan A, MITF, c-kit, DOG1, cytokeratin AE1/AE3, h-caldesmon, STAT6, CD68, CD31, Factor 8, and ERG, making diagnoses of PEComa, GIST, SFT, and angiosarcoma unlikely." (PMID 34797454, 2021).
arrhythmogenic right ventricular cardiomyopathy (8 papers, 2013 to 2026). "Several mutations of the desmin gene are associated with severe muscle diseases like arrhythmogenic right ventricular cardiomyopathy (ARVC)." (PMID 24062977, 2013). "In addition, desmin mutations have recently been found in a subset of patients suffering from arrhythmogenic right ventricular cardiomyopathy (ARVC)." (PMID 33923914, 2021). "Mutations in the intermediate filament protein desmin can typically result in formation of large protein aggregates and thereby are linked to dilated cardiomyopathy, restrictive cardiomyopathy, arrhythmogenic right ventricular cardiomyopathy, and rarely HCM." (PMID 33557094, 2021). "Genetic variants in desmosomal proteins (e.g., PKP2, DSP, DSG2, DSC2) are strongly associated with arrhythmogenic right ventricular cardiomyopathy (ARVC), while mutations in sarcomeric and cytoskeletal genes (e.g., MYH7, LMNA, DES) are linked to hypertrophic and dilated cardiomyopathies." (PMID 41596321, 2026).
cardiac hypertrophy (8 papers, 2014 to 2025). "Earlier experimental studies have remarkably described the role of cytoskeletal alterations of desmin and microtubules in cardiac hypertrophy and failure." (PMID 33806909, 2021). "In addition, we observed that genes associated with cardiac hypertrophy, such as NPPA, NPPB, TNNC1, and DES, were markedly upregulated in the mutant compared with WT iPSC-CMs." (PMID 40779454, 2025). "The results found in our study that upregulation of desmin during the stage of cardiac hypertrophy and HF with impaired diastolic pressure, and upregulation of microtubule‐associated protein 4 in the period of HF with decreased ejection fraction can also prove these conclusions." (PMID 35048506, 2022). "In the present study, the desmin expression in the experimental group is 1.62 times compared with that in the control group, which we conjectured is because of the longer course of disease and the more significant myocardial hypertrophy in patients with RHD." (PMID 24738046, 2014). "Although there has been no report of CS-induced up-regulation of desmin expression in the myocardium, the increased desmin might play an important role in CS-induced cardiac hypertrophy." (PMID 33139745, 2020).
glomerular disease (8 papers, 2012 to 2024). "In fact, upregulation of desmin constitutes one of the key features of podocyte injury associated glomerular diseases." (PMID 39840112, 2024). "Desmin, an intermediate filament protein, has been proposed as an indicator for podocyte injury, and its expression has usually been elevated in glomerular disorders involving podocyte damage." (PMID 37401969, 2024). "Downregulation of nephrin and upregulation of desmin are observed in clinical cases and experimental models with several types of glomerular disease such as MCD, FSGS, MN, lupus nephritis, and diabetic kidney disease." (PMID 39408958, 2024). "UNX was associated with significant renal fibrotic and functional changes and proteinuria, as well as increased renal desmin expression, indicating an ongoing process of podocyte injury and glomerular disease." (PMID 36420617, 2023). "The assessment of normal slit diaphragm component such as podocin and injured podocyte marker, desmin are now therefore considered as two major sensitive markers of podocyte injury and subsequently glomerulopathy in renal diseases." (PMID 23024785, 2012). "However, in different experimental rodent models with glomerular disease, increased glomerular desmin staining is recognized as a marker of podocyte dedifferentiation and injury." (PMID 34561469, 2021). "However, in different experimental models of mice and rats with glomerular disease, increased glomerular desmin staining is recognized as a marker of podocyte dedifferentiation and injury and is followed by decreased nuclear WT1 expression and loss of slit diaphragm proteins." (PMID 32982795, 2020). "Desmin is one such mesenchymal marker that is upregulated by TGF-B1, moreover, desmin upregulation by podocytes is seen in glomerular diseases where podocyte damage is a key feature." (PMID 25324828, 2014).
liposarcoma (8 papers, 2013 to 2025). A usually painless malignant tumor that arises from adipose tissue. "Tumor cells do not express epithelial (CK), myogenic (desmin, SMA), neurogenic (CD56, NSE) markers, well-differentiated/dedifferentiated liposarcoma markers (MDM2, CDK4, p16), or solitary fibrous tumor (SFT) markers (β-catenin, STAT6)." (PMID 41458523, 2025).
neuroblastoma (8 papers, 2009 to 2025). Neuroblastoma (NB) is the most common solid, extracranial childhood tumor. "Neuroblastoma often shows synaptophysin and chromogranin, while desmoplastic small round cell tumors co-express cytokeratins and desmin." (PMID 40084340, 2025). "Malignant mesothelioma and neuroblastoma were also excluded because desmin-positive nuclei were present." (PMID 34193155, 2021). "The lesion revealed positive immunoexpression for vimentin and CD99 and negative immunostaining for desmin, CD45, cytokeratin, and neuroblastoma protein, suggesting, then, the diagnosis of PNET." (PMID 22242031, 2011). "Neuroblastomas are positive for neuroendocrine markers and negative for CK, WT1, and desmin." (PMID 34193155, 2021).
desmoid tumor (7 papers, 2012 to 2025). A desmoid tumor (DT) is a benign, locally invasive soft tissue tumor associated with a high recurrence rate but with no metastatic potential. "Microscopically, the tumor was composed of fibroblast, myofibroblast, and infiltrating the inflammatory cell and diagnosed as desmoid tumor by immunostaining (desmin+/−, β-catenin+, CD117−, vimentin+)." (PMID 30820780, 2019). "Immunostaining showed negative results for c-kit, CD34, desmin, and S-100, while positive results for β-catenin confirmed the diagnosis of a desmoid tumor." (PMID 40124320, 2025). "Immunohistochemistry can assist in the histologic diagnosis of desmoid tumors, as spindle cells typically show positive staining for vimentin, smooth muscle actin, and nuclear beta-catenin, while generally being negative for desmin, cytokeratins, and S-100." (PMID 40349498, 2025). "Unlike desmoid-type fibromatosis, these tumors are S-100 protein positive and they do not express myogenic markers (α-smooth muscle actin or desmin)." (PMID 25349618, 2014). "Pathological examination revealed atypical cells with spindle-shaped nuclei and collagen fiber hyperplasia in the stroma, and immunostaining was negative for c-kit, CD34, desmin, S-100, and positive for β-catenin, leading to a confirmed diagnosis of desmoid tumor." (PMID 40124320, 2025).
malignant peripheral nerve sheath tumor (7 papers, 2012 to 2025). Malignant peripheral nerve sheath tumor (MPNST) is a rare and often aggressive soft tissue sarcoma occurring in a wide range of anatomical sites. "Malignant schwannomas show positive staining for vimentin and CD56 and negative staining for CK, LCA, CD34, SMA, desmin, chromogranin, and synaptophysin." (PMID 25276456, 2014).
small cell carcinoma (7 papers, 2011 to 2025). A neuroendocrine carcinoma composed of small malignant cells which are often said to resemble "oat cells" under the microscope. "Small cell carcinoma often lacks desmoplastic stroma and is not immunoreactive with desmin." (PMID 21696639, 2011). "Because DSRCT is composed of small nests with cohesive small to medium-sized cells and shows immunoreactivity for epithelial markers, it might be diagnosed as carcinomas, such as small cell carcinoma, poorly differentiated carcinoma, undifferentiated carcinoma, without staining for desmin." (PMID 31103034, 2019). "Small-cell carcinomas are positive for IHC, CK, TTF1, and neuroendocrine markers but negative for desmin." (PMID 34193155, 2021).
breast carcinoma (6 papers, 2012 to 2024). "These activities of morphine on endothelial cells and pericytes correlate with an increase in angiogenesis, vessel associated-desmin and -PDDGFR-β expressing pericytes in transgenic mice with breast cancer." (PMID 22315595, 2012). "In sections of mammary tumors from 16-week old MMTV-PyMT mice, NG2 expression is seen on desmin-positive pericytes that are closely associated with CD31-positive endothelial cells in the tumor microvasculature." (PMID 22531600, 2012). "Caveolin-1, Desmin, microfibril associated glycoprotein 4, fibrillin 1 and collagenα-1 have been identified as potential biomarkers that can discriminate metastatic from non-metastatic sentinel lymph nodes in early breast cancer." (PMID 35599267, 2022).
colorectal cancer (6 papers, 2009 to 2025). A primary or metastatic malignant neoplasm that affects the colon or rectum. "In contrast to SMA stain which has a wider natural range of variability between tumours, desmin, as a stromal stain in colorectal cancer, is skewed towards the underexpressed range." (PMID 38186746, 2024). "The aim of our study was to evaluate the diagnosis of desmoplastic reaction (DR) by immunostaining for α-smooth muscle actin (αSMA) and desmin, for predicting the depth of submucosal invasion in biopsy specimens of early colorectal carcinomas (CRCs)." (PMID 23799364, 2013). "However, increased levels of desmin in tumor stroma have been related to advanced stages of colorectal cancer." (PMID 30123423, 2018). "In contrast to the desmin promoter, the C512 promoter was also active in monocyte-derived DC and LC (around 10% of E-GFP+ cells) and in a human colorectal carcinoma (HCT116) (data not shown)." (PMID 19173717, 2009).